EGFR (epidermal growth factor receptor)
Diseases named in the same sentence as EGFR in open-access papers (continued):
Sharing a sentence is not in itself a finding about the gene and the disease.
tumor (continued). "HER2Bi- or EGFRBi-armed anti-CD19 CAR T cells displayed specific cytotoxicity toward multiple HER2+/EGFR+/CD19- tumor targets in long-term serial killing assays." (PMID 35093187, 2022). "In particular, the infiltrating CD8+ T cell levels are significantly different between RAS‐MAPK and EGFR groups in tumor parenchyma (p‐value = 0.01)." (PMID 35150094, 2022). "MiR-30a-5p interacts with the MET and EGFR pathways thus being an indirect suppressor of tumor growth." (PMID 35200568, 2022). "Armored EVs demonstrated increased binding to EGFR-overexpressing tumor cells in vitro, as well as prolonged circulation time in vivo." (PMID 35054611, 2022). "A tumour absorption and tumour visualisation study with anti-EGFR-coated gold nanoparticles of 20 nm in size demonstrated high tumour uptake, while gold nanoparticles of 50 nm in size demonstrated the greatest CT contrast enhancement." (PMID 36557793, 2022). "During treatment, the growth of tumor cells will be retarded, leading to the decrease of EGFR activity." (PMID 35105871, 2022). "ERBB receptor feedback inhibitor 1(ERRFI1) was known as a tumor suppressor, and initiates cell growth by directly inhibiting the epidermal growth factor receptor and its downstream pathway." (PMID 36524001, 2022). "Our results underscore the importance of adjusting the EGFR affinity of EGFR-targeted ITs based on EGFR expression levels on target tumors to maximize the therapeutic window, while reducing the on-target/off-tumor adverse effects." (PMID 36555466, 2022). "Next-generation sequencing (NGS) revealed other than STK11 germline mutation, the tumor also harbors GNAS somatic mutation at codon 478 and EGFR amplification." (PMID 36578081, 2022). "Although over 90% of HNSCC tumors overexpress EGFR, attempts to replace cytotoxic treatments with anti-EGFR agents have failed due to alternative signaling pathways and inter-tumor heterogeneity." (PMID 35154483, 2022). "Tumor cells often possess EGFR amplification or overactive mutants of EGFR, such as del 19 and L858R, which leads to greater sensitivity to gefitinib and erlotinib." (PMID 35814475, 2022). "In this setting, tumor cells are attracted to the epidermal growth factor receptor (EGFR) oncogene, and then treatment options include cetuximab or panitumumab." (PMID 35203586, 2022). "Particular targets of interest for ADCs are human epidermal growth factor receptor (EGFR/HER) family of genes (e.g., EGFR, HER2, HER3) with an alteration that is often associated with the initiation and maintenance of tumor growth." (PMID 36137139, 2022). "EGFR is a transmembrane receptor tyrosine kinase that promotes tumour cell proliferation, angiogenesis and invasion." (PMID 35908284, 2022). "In another in vivo model, a significant delay in tumor growth and an improved survival rate were obtained using the anti-EGFR-TiO2-UCNs conjugate compared to conventional chlorin-e6 (Ce6) treatment." (PMID 35213974, 2022). "For example, miR-7, which acts as a tumor suppressor, directly targets EGFR and can independently suppress this signaling pathway." (PMID 35330864, 2022). "We found a significant upregulation of EGFR in HCC tissues than in their adjacent non-tumor tissues." (PMID 35847904, 2022). "Specifically, three of these five tumour cell lines that performed EGFR-dependent aerotaxis were Basal B and two of the five were Luminal." (PMID 36380366, 2022).
tumor (continued). "Re-analysis of eight primary GBM by MICS showed the broadest and/or strongest expression for GD2, EGFR and cMET on tumor cells, but also a broad inter- and intratumor diversity." (PMID 35115587, 2022). "This study provided a clue for the possible enhancement of the anti-tumor activity of EGFR inhibitors through blocking SCD1 activity." (PMID 35159223, 2022). "It is supposed that EGFR-TKIs, such as gefitinib, downregulate the PD-L1 expression in the tumor microenvironment." (PMID 35745666, 2022). "Authors suggested a non-redundant cooperation of CTNNB1 with PI3CA alterations to promote tumor metastasis or limit EGFR inhibitor response." (PMID 35463360, 2022). "According to some studies, EGFR is associated with PRL secretion, tumor size and invasion, and risk of recurrence in human PRL adenomas and in animal models." (PMID 35454025, 2022). "EGFR activation increases PD-L1 expression in tumor cells, inducing T cell apoptosis and immune escape." (PMID 35742933, 2022). "Enhanced IL-6 secretion is tightly correlated with the activation of ligand-mediated EGFR activation to promote the inflammatory tumor microenvironment of advanced-stage epithelial ovarian cancers." (PMID 36438839, 2022). "EGFR is amplified in up to 60% of GBM cases, with most of these tumours also harbouring EGFR deletion and point mutations." (PMID 36497413, 2022). "Aberrant activation of epidermal growth factor receptor (EGFR) signaling pathways promoting tumor growth and progression has been extensively reported in a majority of human cancers." (PMID 35890277, 2022). "We observed that EGFR inhibition induces a proinflammatory immune response with increased proliferation and activation of tumour-infiltrated T-cells." (PMID 36010935, 2022). "For example, it has been shown that oncogenic epidermal growth factor receptor (EGFR) and EGFR variant III (EGFRvIII) were detectable in EVs isolated from tumor cells both in vitro and in vivo." (PMID 35454874, 2022). "This is a novel approach evaluating the effects of continuing EGFR inhibition for metastatic CRC beyond tumor progression to a first-line panitumumab-containing treatment." (PMID 35761123, 2022). "We collated a total of 159 tumor samples bearing BRAF mutations, 133 with NRAS mutations, 303 with KRAS mutations, and 96 with EGFR mutations from the URMC NGS database from June 2020 to July 2021." (PMID 35627184, 2022). "This is a hybrid-capture based DNA panel that detects mutations in EGFR, KRAS and MET, but requires at least 200 nanograms of DNA with a minimum tumor content of 20%." (PMID 36290901, 2022). "Overexpression of EGFR occurs in ~60% of NSCLC patients and is associated with poor differentiation, increased tumor proliferation, higher incidence of metastases, and lower efficacy." (PMID 36059606, 2022). "The expression of p-EGFR and p-AKT decreased in CRC cells after DCZ0415 treatment suggesting that the anti-tumor effect of DCZ0415 was involved in the EGFR/AKT signaling pathway." (PMID 35075117, 2022). "By fluorescence microscopy analysis, BALB/c nude mice with SKOV-3 tumors treated with rhodamine-labeled anti-EGFR formulations showed increased fluorescence intensity in the tumor region, showing specific targeting." (PMID 35456655, 2022). "Inhibition of β-catenin significantly reduces tumor burdens and improves recurrence-free survival as well as overall survival outcomes in xenograft models of EGFR-TKI-resistant NSCLC cells." (PMID 35301287, 2022). "Using single-cell transcriptomics and flow cytometry, we unveiled large-scale comprehensive longitudinal changes in immune cell composition throughout tumor progression in an epidermal growth factor receptor-driven genetic mouse GBM model." (PMID 35624211, 2022). "As a crucial “controller” that is related to the inhibition of tumor cell proliferation, angiogenesis, invasion, metastasis, and apoptosis, EGFR actively participates in malignant disease progression." (PMID 35840984, 2022).
tumor (continued). "In this study, we also confirmed TRAF4 as an accelerator of EGFR activation and its critical role in tumor genesis of NSCLC, as per the published data." (PMID 35748027, 2022). "In contrast, mice treated with the combination of ATM and EGFR inhibitors displayed sustained tumor regressions that lasted throughout the length of the study." (PMID 35353542, 2022). "In vivo analysis exhibited higher drug concentrations in tumor site when EGFR peptide modified nanoparticles were used alongside the application of external magnetic field when compared to free drug and modified nanoparticles without magnetism." (PMID 35248080, 2022). "The dimerization of EGFR and ErbB2 (HER2) is associated with a poor prognosis and with cell invasion in a range of tumours." (PMID 35781872, 2022). "The comparison of the primary tumor and its relapse showed stable EGFR expression in two patients (#10 and #16) on the protein level." (PMID 36555474, 2022). "Through fusion with glycosylphosphatidylinositol anchors, anti-epidermal growth factor receptor (EGFR) nanobodies were strongly enriched in EVs and greatly improved the capacity of targeting tumor cells." (PMID 36744207, 2022). "There were no statistical differences for age, gender, smoking history, first-line therapies, primary tumor sizes, TNM stages and EGFR mutation types between these two groups." (PMID 36232650, 2022). "EGFR inhibitors were observed to reduce tumor cells with high expression of EGFRvIII in vitro and in vivo, but the cells rebounded when the treatment was discontinued, beyond the classical genetic explanations." (PMID 35614494, 2022). "ctDNA profiling has also enabled tracking of clonal variations in patients with CRC, assisting in real-time monitoring of tumor progression and therapeutic resistance against EGFR blockade." (PMID 35303879, 2022). "Consistently, both doxycycline and A37 decreased the activity of EGFR signalling and the levels of proliferation markers and enhanced apoptosis of xenograft tumours." (PMID 36504325, 2022). "Multiple tumor driver genes that are associated with spermatogenesis pathway such as mTOR, EZH2, NF2, DCC and MLF1 had high enrichment score in the EGFR group." (PMID 35428753, 2022). "The combination of PNA-mediated clamping PCR and the PANAMutyperTM R EGFR kit with PNA clamping-assisted fluorescence melting curve analysis produced 91.7% concordance with the results from a tumor biopsy." (PMID 36552956, 2022). "Next, the Pearson correlation analysis between FBXW2 and EGFR expressions in human PCa tumor samples showed that high EGFR levels had low FBXW2 expression (P = 0.001, r = − 0.572), and vice versa." (PMID 35499593, 2022). "Hematoxylin and eosin (HE) staining, immunohistochemical staining, and immunofluorescence staining of tumor tissues showed that CDCA plus sorafenib had a significant inhibitory effect on EGFR expression." (PMID 35252007, 2022). "Monoclonal antibodies against the vascular endothelial growth factor (VEGF) or, in patients with KRAS/NRAS wild-type tumours, against the epidermal growth factor receptor (EGFR) are commonly added to chemotherapy in mCRC." (PMID 35574322, 2022). "Previous research also reported that inhibiting EGFR phosphorylation levels can decrease tumor cell proliferation." (PMID 36246406, 2022). "Accumulating evidence shows one of the main reasons for resistance to EGFR-TKIs is induction of autophagy in tumor cells." (PMID 35186935, 2022). "Other truncating mutations of tumor related genes (APC, BRCA1, EGFR, FLT4, etc) were also decreased rapidly during treatment." (PMID 36341335, 2022). "It was revealed that stimulation with EGF induced the dissociation of E-cadherin complexes from actin, stressing the role of EGFR signaling in cell–cell adhesion and tumor progression." (PMID 35216384, 2022).
tumor (continued). "As the Ras/MAPK pathway regulated by RTKs played an important role in tumor metastasis, the function of EGFR/MET in regulating the Ras/MAPK pathway will be further investigated in our subsequent research." (PMID 35428350, 2022). "Genetic profiling of brain metastatic tumors and their primary tumor has identified the activation of the PI3K and HER2/EGFR pathways, amongst others, in the metastasizing tumor." (PMID 36507516, 2022). "The distinct change of VEGF secretion following the suppression of EGFR signaling pathway in NSCLC cells suggested an indirect influence of EGFR TKIs on tumor vessels." (PMID 35501907, 2022). "The studies employing the EGFR mutant tumor syngrafts similarly showed that both the JHU083 and the EVax were effective in reducing tumor growth." (PMID 35861366, 2022). "The Two-in-One antibody demonstrated specific cellular binding properties on EGFR- and PD-L1-expressing tumor cells, as well as inhibition of EGFR-dependent signal transduction and blockage of the PD-1/PD-L1 interaction." (PMID 35479092, 2022). "To overcome this limitation, we developed a STING agonist, IMSA172, which can be conjugated to a tumor-targeting agent such as an antibody against EGFR." (PMID 36442099, 2022). "Through the tumor pathway score, we found that the intermediate monocytes had higher scores of NF-κB, hypoxia, EGFR, and TGF-β signal transduction pathway activity, while classical monocytes had higher PI3K signal transduction scores." (PMID 36304995, 2022). "Several sets, including those for cell migration, ZEB1 targets, EGFR signaling, lin genes silenced by the tumor microenvironment, and CDH1 targets, were all closely linked to cancer." (PMID 35645615, 2022). "Monotherapy with RGR-TRAIL and EGFR-targeted PDT showed only mild to moderate tumor growth suppression, whereas two out of ten tumor xenografts were eradicated by the combination therapy." (PMID 35635308, 2022). "It was found that A549 ​cells showed resistance against gefitinib, an epidermal growth factor receptor (EGFR)-targeted anti-tumour drug." (PMID 37360644, 2022). "In an interesting review article, Yi and colleagues discussed the role of EGFR tyrosine kinase inhibitors in targeted nanoplatforms for tumor treatment." (PMID 36096856, 2022). "Anti-EGFR mAb (e.g., Cetuximab and Panitumumab) are conjugated in liposomal formulations to induce apoptosis in tumor cells by blocking ligand binding and receptor dimerization." (PMID 35456655, 2022). "It has been shown that molecular-targeted drugs such as EGFR-TKIs are in two different states: “on-target” and “off-target,” and the molecular mechanisms of tumor resistance to these states are different." (PMID 35684449, 2022). "Possible reasons for resistance to EGFR/EGFRvIII-targeted therapy are blood–brain barrier, tumor heterogeneity, extrachromosomal localization of EGFR, and EGFRvIII amplicons in double minutes, and mutation of genes in downstream pathways." (PMID 35486213, 2022). "Owing to its low affinity for target cells, nimotuzumab binds preferentially to tumour cells that overexpress EGFR, thereby reducing the effect on normal cells with low levels of EGFR; thus, nimotuzumab has few serious adverse effects, specifically rashes." (PMID 36263226, 2022). "For example, in the two crucial gene sets Zeb1 and EGFR, Zeb1 is identified as one of the key EMT genes, and its overexpression is linked to tumor metastasis." (PMID 35645615, 2022). "This molecular biological difference between exon 19 deletions and L858R affects rapid tumor progression and sensitivity to EGFR‐TKI." (PMID 34904383, 2022). "The co-occurrence of both EGFR mutation and MET amplification, particularly at baseline, indicates a more complex genetic heterogeneity of the tumor in these patients." (PMID 34953403, 2022).
tumor (continued). "EGFR activation was positively correlated with tumor progression, thus enabling the evaluation of therapeutic progress." (PMID 35105871, 2022). "In pre-clinical CAR-T work, it has previously been shown that the use of lower affinity EGFR ABDs can improve CAR-T selectivity for overexpressing tumor cells over normal tissues." (PMID 35935988, 2022). "CXCL10 from BAL fluid significantly decreased when tumors developed; however, EGFR-TKI treatment increased CXCL10 expression levels according to tumor regression." (PMID 36612121, 2022). "Compared with other imaging techniques, our proposed method has the unique capability of targeting two key components of tumor microenvironment and differentiating IDH mutation, 1p/19q co-deletion, and EGFR amplification simultaneously." (PMID 35626127, 2022). "Multiple doses of 50 μg IgA2 EGFR antibody restricted tumor growth in an A431 lung carcinoma SCID model in a FcαRI dependent manner." (PMID 35865547, 2022). "The present results show that mice receiving either supplemental FO/Se or an EGFR inhibitor have significantly lower expression of Ki67 and the cell-cycle marker proteins cyclin D1/E than untreated tumor-bearing mice." (PMID 36547898, 2022). "In some carcinomas, glycoproteins such as the EGFR and ErbB2 function as critical oncogenes that consistently drive the tumor phenotype." (PMID 35371997, 2022). "From day 13 on, bioluminescence became detectable in the spleen and other organs of EGFR CAR T cell-treated cohorts indicating that the T cells were either leaving the tumor site or amplifying in other organs to detectable levels." (PMID 35836798, 2022). "ENZR tumors were predicted to be more sensitive to EGFR targeting drugs than any other tumor type in the study, with sapitinib having the most profound effect." (PMID 36167836, 2022). "Tumor or metastatic lymph nodes are smaller after EGFR TKIs compared to their dimension before treatment." (PMID 35522668, 2022). "In a mouse CRC xenograft model, combined blocking of VEGF and EGFR significantly inhibited tumor growth and angiogenesis." (PMID 35740594, 2022). "In the presence of CAFs, tumor cells also displayed resistance to cetuximab, a monoclonal antibody therapy targeting epidermal growth factor receptor (EGFR)." (PMID 36627901, 2022). "These clinical data are consistent with most of our experimental findings showing that genetic inactivation of RBM10 limits the initial apoptotic response in EGFR-mutant tumor cells." (PMID 35579943, 2022). "The TIMER database was utilised to evaluate the correlations of the CENPF expression with the tumor infiltering immune cells and the known EGFR-TKI resistance related genes." (PMID 35154456, 2022). "When combining EGFR inhibition with ICB, we observed a trend to faster antitumour response and slower outgrowth of tumours after relapse, compared to EGFR inhibition alone." (PMID 36010935, 2022). "A new clinical trial is currently underway combining CAR T cell therapy with mAb806 to target amplified EGFR and EGFRvIII with more tumour specificity." (PMID 36497413, 2022). "The combination of a MET inhibitor with an EGFR-TKI attenuated tumour growth more significantly than either single-drug treatment." (PMID 35101055, 2022). "Taken together, these data indicate that 1,25(OH)2D3 significantly induced the expression of hCAP18/LL-37 in tumor tissue, while hCAP18/LL-37 decreased the antitumor activity of 1,25(OH)2D3 partly by activating the EGFR/HER2/Akt signaling pathway." (PMID 35039485, 2022). "Anti-EGFR nanobodies fused to lactadherin, which bind to the phosphatidylserine in EVs post-isolation, have been used to target EGFR-positive tumour cells." (PMID 36290464, 2022). "Sufficient tumor material was available from fourteen patients treated with certolizumab (14/18; 78%) for EGFR, KRAS, BRAF, ERBB2, and ALK testing and from ten patients (10/18; 56%) for NGS." (PMID 36241629, 2022).